AGO2 (argonaute RISC catalytic component 2)
Description:
Required for RNA-mediated gene silencing (RNAi) by the RNA-induced silencing complex (RISC). The 'minimal RISC' appears to include AGO2 bound to a short guide RNA such as a microRNA (miRNA) or short interfering RNA (siRNA). These guide RNAs direct RISC to complementary mRNAs that are targets for RISC-mediated gene silencing. The precise mechanism of gene silencing depends on the degree of complementarity between the miRNA or siRNA and its target. Binding of RISC to a perfectly complementary mRNA generally results in silencing due to endonucleolytic cleavage of the mRNA specifically by AGO2. Binding of RISC to a partially complementary mRNA results in silencing through inhibition of translation, and this is independent of endonuclease activity. May inhibit translation initiation by binding to the 7-methylguanosine cap, thereby preventing the recruitment of the translation initiation factor eIF4-E. May also inhibit translation initiation via interaction with EIF6, which itself binds to the 60S ribosomal subunit and prevents its association with the 40S ribosomal subunit. The inhibition of translational initiation leads to the accumulation of the affected mRNA in cytoplasmic processing bodies (P-bodies), where mRNA degradation may subsequently occur. In some cases RISC-mediated translational repression is also observed for miRNAs that perfectly match the 3' untranslated region (3'-UTR). Can also up-regulate the translation of specific mRNAs under certain growth conditions. Binds to the AU element of the 3'-UTR of the TNF mRNA and up-regulates translation under conditions of serum starvation. Also required for transcriptional gene silencing (TGS), in which short RNAs known as antigene RNAs or agRNAs direct the transcriptional repression of complementary promoter regions. (Microbial infection) Upon Sars-CoV-2 infection, associates with viral miRNA-like small RNA, CoV2-miR-O7a, and may repress mRNAs, such as BATF2, to evade the IFN response.
Synonyms: hAgo2; PPD; EIF2C2; Q10; LINC00980; CASC7; LESKRES
Tractability: Small molecule: a structure with a bound ligand is known; a high-quality ligand is known. PROTAC: UniProt records ubiquitination sites on it; ubiquitination databases record sites on it; its protein half-life has been measured; a small molecule that binds it is known.
Target class: Enzyme; Hydrolase
Gene: Protein-coding gene on chromosome 8 (140,520,156 to 140,635,633, reverse strand). Ensembl gene ENSG00000123908.
Subcellular location: Cytoplasm, P-body; Nucleus
Subcellular location (Human Protein Atlas): Cytoplasmic bodies; Cytosol
Pathways (Reactome):
Gene expression (Transcription): MicroRNA (miRNA) biogenesis; Post-transcriptional silencing by small RNAs; Regulation of NPAS4 mRNA translation; Regulation of RUNX1 Expression and Activity; Small interfering RNA (siRNA) biogenesis; Transcriptional regulation by small RNAs
Signal Transduction: Ca2+ pathway; Competing endogenous RNAs (ceRNAs) regulate PTEN translation; Estrogen-dependent gene expression; MAPK6/MAPK4 signaling; MTOR signalling; NR1H3 & NR1H2 regulate gene expression linked to cholesterol transport and efflux; Pre-NOTCH Transcription and Translation; Regulation of PTEN mRNA translation; TGFBR3 expression
Cell-Cell communication: Regulation of CDH1 mRNA translation by microRNAs; Regulation of CDH11 mRNA translation by microRNAs
Developmental Biology: M-decay: degradation of maternal mRNAs by maternally stored factors; Regulation of MITF-M-dependent genes involved in apoptosis
Disease: Nuclear events stimulated by ALK signaling in cancer
Immune System: Regulation of PD-L1(CD274) translation
Gene Ontology:
Molecular function: core promoter sequence-specific DNA binding; double-stranded RNA binding; endoribonuclease activity, cleaving miRNA-paired mRNA; endoribonuclease activity, cleaving siRNA-paired mRNA; miRNA binding; mRNA 3'-UTR AU-rich region binding; mRNA cap binding; protein binding; RNA 7-methylguanosine cap binding; RNA binding; RNA endonuclease activity; RNA polymerase II complex binding; single-stranded RNA binding; siRNA binding; translation initiation factor activity; mRNA binding; nucleic acid binding; RNA endonuclease activity producing 5'-phosphomonoesters, hydrolytic mechanism
Biological process: miRNA processing; miRNA-mediated gene silencing by inhibition of translation; miRNA-mediated gene silencing by mRNA destabilization; negative regulation of translational initiation; P-body assembly; positive regulation of angiogenesis; positive regulation of transcription by RNA polymerase II; positive regulation of translation; positive regulation of trophoblast cell migration; pre-miRNA processing; regulation of synapse maturation; RISC complex assembly; siRNA-mediated gene silencing by mRNA destabilization; negative regulation of amyloid precursor protein biosynthetic process; positive regulation of nuclear-transcribed mRNA catabolic process, deadenylation-dependent decay; positive regulation of nuclear-transcribed mRNA poly(A) tail shortening; regulatory ncRNA-mediated gene silencing; regulatory ncRNA-mediated post-transcriptional gene silencing; translation; regulation of DNA-templated transcription; translational initiation
Cellular component: cytoplasm; cytoplasmic ribonucleoprotein granule; extracellular exosome; glutamatergic synapse; membrane; nucleus; P-body; postsynapse; RISC complex; RISC-loading complex; cytosol; nucleoplasm; dendrite; ribonucleoprotein complex
Genetic constraint (gnomAD): Loss-of-function variants: 5 observed, 103.34 expected, observed/expected ratio (o/e) 0.0484, 90% interval 0.024 to 0.1. The upper end of that interval is the gene's LOEUF score, 0.1, which puts it in group 1 of 6, group 1 being the genes least tolerant of losing a copy. Missense variants: 541 observed, 1,204.7 expected, observed/expected ratio (o/e) 0.45, 90% interval 0.42 to 0.48. Synonymous variants: 449 observed, 485.65 expected, observed/expected ratio (o/e) 0.92, 90% interval 0.86 to 1.
Gene-disease validity (ClinGen):
ClinGen rates the evidence that AGO2 causes each of these diseases.
Lessel-Kreienkamp syndrome (autosomal dominant): Definitive.
Homologues: Orthologues: macaque AGO2 (99% identical), chimpanzee AGO2 (99% identical), dog AGO2 (99% identical), mouse Ago2 (99% identical), guinea pig AGO2 (99% identical), rat Ago2 (99% identical), pig AGO2 (99% identical), tropical clawed frog ago2 (97% identical), zebrafish ago2 (92% identical), rabbit AGO2 (84% identical), Drosophila melanogaster AGO1 (75% identical), Caenorhabditis elegans alg-1 (69% identical), and 1 more. Paralogues in human: AGO1 (82% identical), AGO3 (80% identical), AGO4 (78% identical).
Diseases named in the same sentence as AGO2 in open-access papers:
AGO2 is named in the same sentence as 213 diseases in open-access papers, as found by Europe PMC text mining. Sharing a sentence is not in itself a finding about the gene and the disease. The quoted sentences say what the papers report.
viral infection (77 papers, 2009 to 2025). "We have observed an enhanced viral infection in cells with RNAi defects caused by Dcr-2 or Ago2 knockdown and an increased gene expression in the region with reduced vsiRNA yield caused by the existence of BmNPV p35." (PMID 35251046, 2022). "A significant increase in Ago-2 basal levels between w1118 and Oregon-R was observed, but it cannot explain the difference in susceptibility to virus infection observed for these strains." (PMID 32194567, 2020). "The importance of RNAi in antiviral defense has been demonstrated using fly mutants deficient in Dicer-2, R2D2, and Ago2, which are more susceptible to virus infection and accumulate higher virus levels than wildtype flies." (PMID 31100912, 2019). "Later, flies deficient in ago-2 were shown to be hypersensitive to viral infection, further implicating particular members of the RNAi pathway in antiviral defense." (PMID 30060518, 2018). "The Ago2-deficient Aag2 cell line was derived from this cell line and as persistent virus infections can be lost when clonal cell lines are created, potential differences between both viromes may exist." (PMID 39845567, 2025). "Dicer2, R2D2, and Ago2 have been shown to be essential for the fly antiviral defense, suggesting that the loss of factors involved in mitochondrial RNA metabolism can result in a hypersensitivity to viral infections." (PMID 31365523, 2019). "This hints that bi-cistronic Ago2/AgoshRNA plasmids will also be useful in cells in which Dicer is mutated, depleted or inhibited, a phenomenon that is increasingly found in human cancers or other diseases including viral infections." (PMID 24049077, 2013). "However, it is noteworthy that in the case of viral infection, cellular siRNA pathway was not completely blocked by p35, based on the fact that in the presence of p35, RNAi defects caused by Dcr-2 or Ago2 knockdown still led to significantly enhanced viral infection and accumulation." (PMID 35251046, 2022). "To confirm the nuclear localization of AGO2 during viral infection, we utilized a fluorescently tagged PR8 virus strain, which has mCherry inserted within the NS1 protein, and performed confocal microscopy." (PMID 40219968, 2025). "Viral infection led to the generation of vsiRNA and showed higher replication in AGO2-/- cells compared to wild-type (WT) cells, confirming the antiviral role of the RNAi pathway against SFTSV infection." (PMID 40013801, 2025). "Together, the effects of AGO2 on viral infection can be governed by diverse variables such as viral quantity, host cell type, expression level, and subcellular localization of AGO2." (PMID 40219968, 2025). "Immunoblot analysis demonstrated that AGO2 deficiency significantly increased the phosphorylation of IRF3 and STAT1 upon virus infection." (PMID 40949099, 2025). "Further studies are needed to fully understand the role of AGO2 and other host proteins in the immune response to viral infections and to develop novel therapeutic strategies targeting these proteins to enhance antiviral defense." (PMID 40949099, 2025). "Later, the critical role of the N. benthamiana AGO2 orthologue in limiting virus infections was also corroborated using genome-edited ago2 mutant plants." (PMID 38898307, 2024). "Previous studies provided evidence that viral infection or early differentiation, involve AGO2 nuclear function and that AGO2 preferentially binds 3′UTRs and introns within pre-mRNAs." (PMID 38994560, 2024). "Previously, the influence of the ethylene signaling pathway on increasing the expression of the AGO2 gene during the development of resistance to viral infection was shown." (PMID 38138127, 2023). "It should be of note that gene expression was estimated between fly lines of the same background in this study to ensure similar basal levels of Dicer-2 and Ago-2 before viral infection." (PMID 35844546, 2022).
viral infection (continued). "In the current work we showed that, although their transcripts remain unchanged, Dcr-2 and Ago-2 protein levels change after injection-related stress and viral infection." (PMID 32194567, 2020). "Altogether, the results show that Dcr-2 and Ago-2 protein levels change promptly upon virus infection." (PMID 32194567, 2020). "To explore if mRNA expression levels correlate with proteins levels upon viral infection, we quantified the expression of Dcr-2 and Ago-2 proteins." (PMID 32194567, 2020). "In D. melanogaster, hemocytes control viral infections by clearing virus-infected cells by phagocytosis and by providing an Ago-2-dependent protection to naive cells, resulting in higher viral loads in flies depleted of hemocytes." (PMID 32269152, 2020). "Viral infection of Rag1−/− mice induces production of vsiRNA-RISC active to direct specific RNA slicing by Ago2." (PMID 32753500, 2020). "We propose that miR403 in conjunction with other AGO2-derived vasiRNAs contributes to maintain AGO2 under functional levels when it is transcriptionally activated in response to virus infection." (PMID 33230160, 2020). "AGO2 also takes part in the plant antiviral response, as highlighted by the hypersusceptible of the Arabidopsis ago2 mutants to viral infections." (PMID 33321742, 2020). "Similar to our previous study that examined the honey bee transcriptional response to SINV-GFP infection, we determined that virus infection resulted in increased expression of honey bee immune genes including ago-2, dcr-like, and mf116383." (PMID 32098425, 2020). "Components of the RNAi machinery (Ago-2, Dcr-2, TSN) showed a transcriptional response after ingestion of a blood meal and after oral viral infection, while also changes in Ago-2 protein levels were observed." (PMID 31354527, 2019). "Our finding of significant upregulation of the expression of AGO2 in GpSGHV-injected flies suggests that the virus infection induces the host’s siRNA-mediated response, presumably to inhibit the virus infection." (PMID 30470195, 2018). "We further assessed the impact of AGO2 knockdown on virus infection by RT-qPCR quantification of four selected GpSGHV genes, i.e. odv-e66, dnapol, maltodextrin glycosyltransferase (a tegument gene) and SGHV091 (a capsid gene)." (PMID 30470195, 2018). "We then assessed the effect of AGO2 knockdown on virus infection by quantifying expression levels of the selected viral genes, odv-e66, DNApol, SGHV038 and SGHV091." (PMID 30470195, 2018). "Similar to honey bees, the bumble bee (B. terrestris) RNAi machinery (i.e., ago-2, dicer-2) exhibits slightly increased expression in the context of virus infection (i.e., IAPV and SBPV)." (PMID 30060518, 2018). "Three females and 3 males were sampled from each of the described treatments at 1 h post injection, and at 7, 14 and 21 days post injection to determine the effect of AGO2 knockdown on virus infection." (PMID 30470195, 2018). "The transcript levels of genes for core components DCR2 and AGO2 of the siRNA pathway were significantly upregulated after viral infection." (PMID 26864546, 2016). "Upon viral infection on viruliferous mites-infected plants, we observed induction of SA pathway and AGO2-mediated RNA silencing and reduction of the JA/ET defenses." (PMID 27933078, 2016). "To determine the effect of viral infection on the sorting system, we compared the content of deep-sequenced RNA extracted from immunoprecipitation experiments with the Ago1 and Ago2 proteins using Epstein–Barr virus (EBV)-infected cells." (PMID 24627180, 2014). "We confirmed that Argonaute-2 (AGO2), the core component of the silencing complex, is in association with ribosomes regardless of viral infection." (PMID 39899642, 2025).
viral infection (continued). "In general, the translocation of AGO2 from the cytoplasm to the nucleus is a complex, dynamic process, elicited by a spectrum of cellular stressors, including, but not limited to, cell confluence, DNA damage, activation of oncogenes, and viral infections." (PMID 40219968, 2025). "We observed that AGO2 had strong interactions with the CARD and helicase domains of RIG-I, but only weakly binds to the CTD domain, with all of these associations being slightly decreased in DelNS1 WSN virus infection." (PMID 40949099, 2025). "Thus, a nuanced understanding of the viral infection context is essential to decipher the varied roles of AGO2 in viral infections." (PMID 40219968, 2025). "AGO2 has been demonstrated to be involved in resistance to viral infection." (PMID 36650505, 2023). "A dysregulation of the expression of genes involved in miRNA biogenesis had actually been found in several other viral infections: Dengue virus infection led to a decrease of mRNA levels of DICER, DROSHA, AGO1, and AGO2 in Huh-7 cells and this was associated with increased viral replication." (PMID 37243263, 2023). "Overall, dysregulation of Dicer, Drosha, Ago2 could play an important role in promoting viral infection." (PMID 34715923, 2021). "In agreement, we detected miR393*, which inhibits retrograde transport in Pseudomonas-infected A. thaliana, in our immunoprecipitation from SPMMV-infected leaf extracts indicating that functional miR393*-AGO2 complexes were formed upon viral infection (this work)." (PMID 33925878, 2021). "To investigate whether the priming by BTH of AGO2 for enhanced transcription is associated with the induction of resistance to viral infection, we examined the interaction with CMV(Y) with A. thaliana wild‐type plants and the ago2 mutant." (PMID 33073913, 2021). "Previous studies demonstrated that viral infections trigger Dcr-2 and Ago-2 mRNA expression in Apis mellifera and Bombus terrestris, and several authors suggested that this induction might be an essential feature to deal against infections in insects." (PMID 32194567, 2020). "For these reasons, we hypothesized that variations in Dcr-2 and Ago-2 expression levels upon viral infection could explain the difference in mortality between strains." (PMID 32194567, 2020). "We next asked if the differences in susceptibility and viral accumulation observed between w1118, Oregon-R and yw flies might be due to differences in the basal levels of the siRNA pathway core proteins, Dcr-2 and Ago-2, before viral infection." (PMID 32194567, 2020). "However, the previous exposure to inact-DV in Ae. aegypti larvae enhance the antiviral immune response against DENV in adult mosquitoes, modifying the expression of DCR-2 and AGO-2 after viral infection." (PMID 32317699, 2020). "However, activation of the type I IFN (IFN-I) response by viral infection is inhibitory to miRNA-guided RNA slicing by Ago2 in cell culture, and there are contradictory reports on the antiviral activity of Ago2 in cultured cells (10, –, 12, 16, 23, 31)." (PMID 32753500, 2020). "Moreover, viral infection or treatment with the dsRNA mimic poly I:C induced ADP-ribosylation of AGO2, resulting in inhibition of RISC activity and, thus, decreased siRNA and miRNA silencing activity." (PMID 31100912, 2019). "While this suggests a general viral infection- or replication-associated induction of AGO2, similar to that of AGO1, our data revealed significant differences in the AGO2 mRNA levels at the early infection stage of 2 dpi where the replication levels of CymRSV and Cym19stop are closely comparable." (PMID 29691336, 2018). "Both ago1 and ago2 mutants were hypersensitive to viral infection in plant." (PMID 29601523, 2018). "RNAi is an important immune defense pathway against virus infections in most insects; the up-regulation of miR-184-3p in symptomatically GpSGHV infected flies may responsible to modulate AGO-2 expression and thereby regulate virus replication." (PMID 30233523, 2018).